PPARG (peroxisome proliferator activated receptor gamma)
Diseases named in the same sentence as PPARG in open-access papers (continued):
Sharing a sentence is not in itself a finding about the gene and the disease.
periodontitis (continued). "Further experimental and clinical studies are needed to confirm the findings observed here and to clarify PPARG mRNA and PPAR-γ protein levels through immunohistochemical evaluations, which will contribute to a comprehensive understanding of the role of this important molecule in periodontitis." (PMID 40868279, 2025). "Although several studies investigating the role of SNPs in the PPARG gene in T2DM have been published, to our knowledge, this is the first study to investigate the potential contribution of the PPARG SNPs with the occurrence of periodontitis together with T2DM." (PMID 37047733, 2023).
viral infection (18 papers, 2010 to 2025). "These terms were also related to PPARγ-associated terms in cluster 1, which was the innate immune response and inflammatory response, where they were activated upon virus infection." (PMID 38263024, 2024). "PPARγ activation has been associated with inhibition of some viral infections." (PMID 27382365, 2016). "Further studies to evaluate the effect of the various PPARγ agonists against viral infection will be worthwhile." (PMID 36091002, 2022). "This review aims to provide for the first time an update on our knowledge of the role of PPARγ in viral infections of the brain parenchyma." (PMID 34445581, 2021). "It appears that PPARγ is upregulated in certain viral infections while downregulated in other viral infections." (PMID 35003101, 2021). "Investigations about the outcomes of viral infection in the brain shed new light on PPARγ in the developing and adult brain." (PMID 34445581, 2021). "While PPARγ activation leads to poor prognosis in bacterial infection, it apparently leads to good prognosis in viral infection through its inhibition of hyperimmune response." (PMID 35003101, 2021). "It will update the current knowledge on PPARγ molecular aspects and brain expression, point out recent advances about PPARγ focusing on specific brain issues, and, finally, summarise and discuss knowledge on PPARγ and viral infections of the brain parenchyma." (PMID 34445581, 2021). "Downregulation of macrophage PPARγ signalling and sterol metabolic pathways has been reported earlier in the context of virus infections." (PMID 34220803, 2021). "This assumption is supported by a recent publication demonstrating that pharmacologic PPARγ activation reduced chemokine-driven recruitment and local proliferation of tipDCs during viral infection." (PMID 22629382, 2012). "Similar results were observed in contemporary H3N2 viral infection treated with PPARγ agonist." (PMID 36091002, 2022). "Stimulation of PPARγ by natural or synthetic agonists may modulate the cytokine storm typical of viral infection by preventing cytokine overproduction and the inflammatory cascade." (PMID 36091002, 2022). "The stimulation of PPARγ by natural or synthetic agonists could exert a regulatory role on the cytokine storm typical of virus infections, by preventing the cytokine overproduction and the inflammatory cascade." (PMID 35053112, 2022). "Regardless, PPARγ plays a significant role in the prognosis of viral infections in general." (PMID 35003101, 2021). "Although the role of PPARγ in the regulation of the immune response and inflammation is well established, little is known however about its role in infections of the brain parenchyma, particularly viral infections." (PMID 34445581, 2021). "However, the impact of viral infection on PPARγ activity has been investigated for only a small minority of these pathogens." (PMID 34445581, 2021). "This review aims to provide an update on the role of PPARγ in viral infections of the brain." (PMID 34445581, 2021). "Thus, our results provide evidence for the crosstalk of IRAK-M and viral infection and support earlier findings on the effect of influenza viruses on PPARγ expression and function." (PMID 28118607, 2017). "In the presence of GW (PPARγ antagonist) and AG (AT1 agonist), viral infection was increased remarkably, while AT1 was upregulated and PPARγ was downregulated." (PMID 40810540, 2025). "This study confirmed a key role for PPARγ in neurogenesis and in the pathophysiology of HCMV infection, displaying that viral infection triggers PPARγ levels in NSCs." (PMID 35053112, 2022). "As a recent report identified another PPARγ agonist as inhibiting SARS‐CoV‐2 infection in large compound screening, PPARγ seems to regulate virus infection." (PMID 33822489, 2021). "PPARγ stimulation and N-acetylcysteine (NAC) treatment have been found to interfere with viral infections including rotavirus infection." (PMID 27382365, 2016).
viral infection (continued). "In addition, we wanted to know whether the expression of some cellular proteins previously related with rotavirus infection is responsive to viral infection and treatment with some PPARγ agonists using a synchronous system consisting of small intestinal villi isolated from mice." (PMID 27382365, 2016). "Thus, the importance of PPARγ, APOBEC3G and IFITM3 upon viral infection could not be denied due to their involvement in pathways affecting viral pathogenicity, specifically in viral replication." (PMID 38263024, 2024).
acute kidney injury (17 papers, 2011 to 2025). Sudden and sustained deterioration of the kidney function characterized by decreased glomerular filtration rate, increased serum creatinine or oliguria. "In our study we found significantly increased levels of PPARg in the group with acute kidney injury that had a poor post-transplant outcome." (PMID 38503767, 2024). "Other reports suggested that PPARγ activation protected against renal failure models such as chronic renal allograft damage and ischemia-reperfusion renal injury." (PMID 38745206, 2024). "More importantly, PPARG is a disease-related target in the development of LGT adverse reactions such as renal failure, infrequent menstruation, neutropenia, hepatomegaly, and other reproductive and hepatic toxicity." (PMID 36339610, 2022). "In the present study, the effect of the PPARγ agonist rosiglitazone was investigated in a well-established model of ischemic acute kidney injury." (PMID 22448163, 2012). "Rosiglitazone, a peroxisome proliferator-activated receptor-gamma agonist that induces the expression of many proximal tubular cell transporters, protected rats from tenofovir-induced renal failure and proximal tubular dysfunction." (PMID 21716719, 2011). "Furthermore, increased OS and pro-inflammatory cytokines were reported to down-regulate PPARγ expression during renal failure." (PMID 38745206, 2024). "Additionally, downregulated PPARγ expression may induce ischemia in reperfusion-induced acute kidney injury." (PMID 36339588, 2022). "RT-qPCR validated miRNA and mRNAs included IGFBP2 (respiratory system); MMP9 and PDE4B (nervous system); PPARG (cardiovascular system); AKR1B1, ANXA1, and LNC2/NGAL (acute kidney injury); GFER/ALR (liver); and miR-30c-3p (coagulopathy)." (PMID 34573990, 2021). "BSHX alleviates glomerulosclerosis and tubulointerstitial injury and subsequently reverses renal failure in 5/6 nephrectomy rats, possibly via inhibition of the inflammatory responses mediated by TNF-α, NF-κB, TGF-β1, CTGF, PPARγ, and OPN." (PMID 24864155, 2014).
bladder tumors (17 papers, 2012 to 2025). "Recurrent activating mutations of PPARγ and RXRα have been linked to pro-tumorigenic PPARγ/RXRα pathway activation in luminal bladder tumors." (PMID 39695138, 2024). "Recently, seven recurrent driver gain-of-function PPARγ mutations have been identified in luminal bladder tumors (E3K, S249L, M280I, K164W, and T475M)." (PMID 33716977, 2021). "Of the 21 unique PPARγ mutations identified here in bladder tumors, 6 were recurrent and occurred in both MIBC and NMIBC." (PMID 30651555, 2019). "Taken together, our study highlighted the existence of recurrent driver gain-of-function PPARγ mutations in a particular type of cancer: luminal bladder tumors." (PMID 30651555, 2019). "Secondly, pioglitazone was used for pharmacological activation of PPARγ but was found to be associated with bladder tumors and withdrawn by a few countries." (PMID 30105244, 2018). "RXRα S427F/Y and PPARγ-overexpressing bladder tumors were significantly associated with suppression of immune infiltration and inflammation-related pathways." (PMID 28740126, 2017). "PPARG mutations frequently occur in BC, and a decreased expression of PPARG may potentially facilitate the development of bladder tumors." (PMID 40575382, 2025). "Finally, the function of PPARG has also been linked to the mechanism of action by which BCG inhibits bladder tumor growth." (PMID 31100982, 2019). "Previous reports showed that the abnormal activation of the PPARγ and related signaling events contributed to the overexpression of retinoid X receptors (RXRs) during luminal bladder tumor initiation and progression." (PMID 35071227, 2021). "Recent studies confirmed this observation and showed that claudin-low bladder tumors also upregulated cytokines and chemokines with low expression levels of PPARγ allowing unopposed NF-κB activity." (PMID 32546765, 2020). "In line with previous studies, our data also suggested that PPARγ activation by agonists significantly suppressed bladder tumor growth in vitro and in vivo." (PMID 30845932, 2019). "The upregulation of PPARγ/RXRα transcriptional activity has emerged as a key event in luminal bladder tumors." (PMID 30651555, 2019). "These recurrent PPARγ mutations (p = 0.015) and PPARG amplifications (p = 1.5 × 10–5) were significantly enriched in bladder tumors presenting a PPARγ activation signature, which were mostly luminal tumors (p = 2.2 × 10–16), as shown by Fisher’s exact test." (PMID 30651555, 2019). "To functionally confirm the potential for PPARγ/RXRαS427F/Y to influence chemokine expression and secretion in bladder tumor cells, we profiled the expression/secretion of key inflammatory factors in engineered T24 lines in vitro." (PMID 28740126, 2017). "We further performed a correlation analysis across the TCGA bladder tumors for PPARγ and a curated immune signature including inflammatory factors and immune lineage markers (refer to “Methods”)." (PMID 28740126, 2017). "In addition, the RXRα hotspot mutations stimulate the proliferation of urothelial organoids, render bladder tumor cell growth PPARγ-dependent, and favor tumor evasion by the immune system." (PMID 33716977, 2021). "Given this crucial role of the PPARγ/RXRα pathway in bladder tumors, in this work, we search for other genetic alterations that could drive its activation in both NMIBC and MIBC." (PMID 30651555, 2019). "Our study reveals genomic alterations of PPARG that lead to pro-tumorigenic PPARγ/RXRα pathway activation in luminal bladder tumors and may open the way towards alternative options for treatment." (PMID 30651555, 2019). "In addition to high PPARγ expressing tumors, RXRαS427F/Y positive bladder tumors also showed an anti-correlation with immune lineage markers, immune checkpoint genes, and inflammatory chemokines suggesting that both genotypes may significantly hamper immune infiltration." (PMID 28740126, 2017).
bladder tumors (continued). "We performed immunohistochemistry (IHC) staining for PPARγ and CD8 in a cohort of human bladder tumors (Eisai cohort)." (PMID 28740126, 2017). "In addition, since PPARG plays a critical role in the mechanism of action by which bacillus Calmette-Guérin (BCG) inhibits bladder tumor growth, the decreased level of amplification of the third sample could be explained thanks to the BCG treatment after the second TURB." (PMID 23114535, 2012). "Using the conventional Sanger’s method, we sequenced the PPARG and RXRA exons in 359 bladder tumors (199 of which were NMIBCs) from our CIT series of tumors (carte d’identité des tumeurs) and from a bank of samples collected at Strasbourg hospital, and in 25 bladder cell lines." (PMID 30651555, 2019).
Cirrhosis (17 papers, 2008 to 2025). A chronic disorder of the liver in which liver tissue becomes scarred and is partially replaced by regenerative nodules and fibrotic tissue resulting in loss of liver function. "In hepatic stellate cells PPARγ activation inhibits fibrosis and other cirrhosis-promoting responses." (PMID 34835949, 2021). "Activation of systemic, renal vessel and renal tissue levels of PPARγ by chronic pioglitazone treatment has beneficial effects on the endotoxemia-related TNFα/NFκB-mediated acute and chronic renal inflammation in cirrhosis." (PMID 34831270, 2021). "Systemic activation of peroxisome proliferator-activated receptor gamma (PPARγ) with pioglitazone can suppress inflammation-related splanchnic and pulmonary dysfunction in cirrhosis." (PMID 34831270, 2021). "Activation of systemic, renal tissue and renal vessel levels of PPARγ by chronic pioglitazone treatment has beneficial effects on the endotoxemia-related TNFα/NFκB-mediated acute on chronic renal inflammation in cirrhosis." (PMID 34831270, 2021). "However, the relationship between fatty acids and the expression of hepatic PPARγ during cirrhosis regression remains unknown." (PMID 38178856, 2023). "From 2 transcriptomics datasets representing stepwise carcinogenic process (cirrhosis, dysplasia and HCC), we observed that PPARG expression is unchanged between pre-neoplasic lesions and early HCC." (PMID 41249163, 2025). "Enterocytes: IPA analysis showed significant activation of inflammatory pathways (TNF, IFNG), PPARG/A with gut-liver signaling pathways (FGF21, IGF1R, CREBP) and fatty acid and lipid oxidation in compensated cirrhosis versus controls." (PMID 38369527, 2024). "However, the expression of PPARγ in the liver tissues of patients with HBV-related cirrhosis remains unknown, especially during the regression of cirrhosis." (PMID 38178856, 2023).
diabetic cardiomyopathy (17 papers, 2010 to 2026). Diabetic cardiomyopathy is a disorder of the heart muscle in people with diabetes. "Our findings extend support to the fact that PPARγ and tempol are promising therapeutic targets for diabetic cardiomyopathy." (PMID 20828387, 2010). "It is consistent with the finding that activation of PPARγ improves endothelial function and thereby mitigates the diabetic cardiomyopathy." (PMID 20828387, 2010). "However, in another study reported that ginsenoside Rg3 binds directly to PPARγ, improving adiponectin signaling and ameliorating diabetic cardiomyopathy (DCM) in db/db mice." (PMID 40405893, 2025). "Bioinformatics analyses have suggested that fenofibrate could be a therapeutic agent for diabetic cardiomyopathy and DFU, as the PPARG gene is implicated in both." (PMID 39696281, 2024). "In mice injected with a PPARγ inhibitor, the protective effects of KLF9 knockdown on diabetic cardiomyopathy were counteracted by GW9662 injection." (PMID 36359788, 2022). "A stimulatory role of PPARG on HMGCS2 expression has been observed, for example, in a mouse model of diabetic cardiomyopathy and in intestinal tumor cell lines and normal intestinal organoids." (PMID 32277923, 2020).
Nephropathy (17 papers, 2008 to 2025). A nonspecific term referring to disease or damage of the kidneys. "PPARγ haploinsufficiency aswell as Pro12Ala (P12A) allele polymorphism of PPARγ has a protective role in the development ofdiabetic nephropathy." (PMID 19283081, 2008). "In mice with heterozygous PPARγ mutation, high-fat dietresults in a less severe nephropathy and lipid depositions than in wild typeanimals." (PMID 19283081, 2008). "A murine model of intestinal IRI showed that PPARγ-deficient mice exhibited more severe kidney damage; however, that adverse impact on tissues could be abrogated by the activation of PPARγ." (PMID 33995008, 2021). "However, the dysfunctioned PPARγ is closely associated with the pathogenesis of nephropathy." (PMID 36339588, 2022). "This also confirms that the effect of Nephropathy 1st is achieved by affecting the PPARγ pathway, which is consistent with the reduced PPARγ expression by Nephropathy 1st." (PMID 36339588, 2022). "We found that the PPARy renal expression was significantly lower in the UUO model compared with the control group and treatment with Nephropathy 1st, and the standard drug restored PPARγ expression." (PMID 36339588, 2022). "Mechanistically, Nephropathy 1st promoted the expression of PPARγ and thus activated PPARγ signaling, thereby reducing the pro-fibrotic phenotypes of fibroblasts." (PMID 36339588, 2022). "In our report, we revealed that the therapeutic role of Nephropathy 1st was dependent on the activation of PPARγ signaling." (PMID 36339588, 2022). "The results of the present study extend our earlier observations by demonstrating the efficacy of EGCG in reversing the downregulation of PPARγ in animals with established nephropathy." (PMID 25785827, 2015). "The therapeutic effect of Nephropathy 1st was abrogated by the PPARγ inhibitor GW9662." (PMID 36339588, 2022). "Moreover, PPARγ agonists have significant renoprotective properties in experimental models of nephropathy." (PMID 30012954, 2018). "Therefore, we speculated that Danhong injection reduces kidney damage in diabetic rats partially through the energy metabolism regulation mediated by PPARγ/UCP-1 signaling pathway." (PMID 29849705, 2018). "In NRK-49F cells, we also found that lotensin and Nephropathy 1st reversed the effects of TGF-β1 on the expression of Col-I, FN, PPARγ, and Klotho." (PMID 36339588, 2022). "Lotensin and the medium and high concentrations of Nephropathy 1st increased the levels of PPARγ and klotho in TGF-β1-challenged fibroblasts, suggesting that PPARγ might be involved in the therapeutic effect of Nephropathy 1st." (PMID 36339588, 2022). "Studies have shown that insulin-sensitizing agents, including metformin and PPARγ agonists, are beneficial in preventing kidney damage in both T1DM and T2DM as well as in non-DKD." (PMID 29686650, 2018).